EYA2 (EYA transcriptional coactivator and phosphatase 2)
Diseases named in the same sentence as EYA2 in open-access papers (continued):
Sharing a sentence is not in itself a finding about the gene and the disease.
lung carcinoma (10 papers, 2017 to 2024). "Collectively, these results suggest that high EYA2 expression was associated with poor overall survival in patients with lung cancer." (PMID 29340020, 2017). "In lung cancer, EYA2 promoted tumor cell proliferation through microRNA-93-mediated inhibition of phosphatase and tension homolog." (PMID 30761270, 2019). "The cell growth assay indicated that the proliferation rate of A549 lung cancer cells overexpressed with EYA2 was significantly higher than that of vector control cells at 5 days after plating (*p < 0.05)." (PMID 29340020, 2017). "We further analyzed EYA2 expression according to the histological subtype of the lung cancer tissues." (PMID 29340020, 2017). "Kaplan Meier analysis revealed that lung cancer patients with high expression of EYA2 had a worse overall survival probability (p = 0.029)." (PMID 29340020, 2017). "Collectively, our findings suggest that EYA2 has an oncogenic role in the development of lung cancer." (PMID 29340020, 2017). "The cell growth assay showed that overexpression of EYA2 enhanced lung cancer cell growth, while re-expression of PTEN significantly compromised the growth advantage conferred by EYA2 in A549 cells (*p < 0.05)." (PMID 29340020, 2017). "To address the functional consequence of EYA2 upregulation in lung cancer, we examined the effect of EYA2 on the proliferation of A549 cells." (PMID 29340020, 2017). "In summary, these results indicated that EYA2 promoted cell proliferation via inhibition of PTEN in lung cancer." (PMID 29340020, 2017). "To evaluate the role of EYA2 in lung cancer development, we first examined the mRNA expression levels of EYA2 in five lung cancer datasets (Bhattacharjee’s dataset, GSE3398, GSE7670, GSE3268 and GSE19188) using ONCOMINE database." (PMID 29340020, 2017). "It is therefore safe to conclude that miR-93 is essential for EYA2 to repress the expression of PTEN in lung cancer cells." (PMID 29340020, 2017). "In conclusion, overexpression of EYA2 leads to increased cell proliferation through suppression of PTEN in lung cancer, and EYA2 suppresses PTEN expression via upregulating miR-93." (PMID 29340020, 2017). "Our study not only yields a better understanding of the important role of EYA2 in lung cancer occurrence and progression, but also paves the way for the development of novel therapeutics target." (PMID 29340020, 2017). "EYA1 is overexpressed in Wilms’ tumors, EYA2 is overexpressed in epithelial ovarian cancers and lung carcinoma, and EYA4 overexpression has been detected in MPNST (malignant peripheral nerve sheath tumor)." (PMID 29340020, 2017). "In the present study, we found that EYA2 was up-regulated in lung cancer, and EYA2 led to increased cell proliferation by inhibiting Phosphatase and tensin homologue (PTEN) expression via modulation of miR-93." (PMID 29340020, 2017). "We analyzed the relationship between EYA2 expression and overall survival in patients with lung cancer." (PMID 29340020, 2017). "Lung cancer cells have a hypomethylated EYA2 gene, resulting in overexpression of EYA244." (PMID 37156847, 2023). "Eya2 also promotes the proliferation of lung cancer cells by downregulating PTEN." (PMID 31317026, 2019). "Additionally, survival analysis showed that lung cancer patients with higher expression of EYA2 had a worse overall survival." (PMID 29340020, 2017). "As a result, the inhibition of EYA2 may represent a novel and promising treatment strategy for lung cancer." (PMID 29340020, 2017). "In the subsequent experiment, our data demonstrated that EYA2 could promote lung cancer cell growth both in vitro an in vivo." (PMID 29340020, 2017). "To determine whether EYA2 affect the cell death of lung cancer, we knocked down the endogenous EYA2 in A549 cells and then performed Annexin/PI staining assay." (PMID 29340020, 2017). "Overexpression of miR-30a inhibits migration and invasion via targeting EYA2 in lung cancer." (PMID 29340020, 2017).
lung carcinoma (continued). "Taken together, these results indicated that EYA2 promoted lung cancer cell proliferation in vitro." (PMID 29340020, 2017). "Eyes absent transcriptional cofactor EYA2 has been shown to promote lung cancer cell growth, however, the underlying molecular mechanism is still not fully understood." (PMID 29340020, 2017). "Additionally, survival analysis showed that lung cancer patients with higher EYA2 expression predicted a worse prognosis." (PMID 29340020, 2017). "In the microarray gene expression studies, EYA2 mRNA levels in lung tumor tissues were significantly higher than those in the non-tumor lung tissues, the EYA2 mRNA levels ranged from 1.6- to 13.3-fold increase in lung cancer." (PMID 29340020, 2017). "The results showed that EYA2 could up-regulate the levels of miR-93 and miR-106b in lung cancer cells (*p < 0.05)." (PMID 29340020, 2017). "We examined the role of EYA2 in another lung cancer cell line H1975." (PMID 29340020, 2017). "The EYA2 expression was upregulated in both lung adenocarcinoma (p = 0.012) and lung squamous cell carcinoma (p = 0.005), which was also consistent with results from analysis of different lung cancer datasets." (PMID 29340020, 2017). "In addition, survival analysis indicates that lung cancer patients with high EYA2 expression have a worse overall survival." (PMID 29340020, 2017). "In this study, the increased expression of EYA2 was detected in lung cancer." (PMID 29340020, 2017). "Together, these data suggested that EYA2 was up-regulated in lung cancer." (PMID 29340020, 2017). "Similarly, in the GSE30219 dataset, high level of EYA2 also conferred poor prognosis in lung cancer patients (p = 0.0083)." (PMID 29340020, 2017). "Moreover, EYA2 has been shown to promote cell growth in lung cancer." (PMID 29340020, 2017). "Forced expression of EYA2 could enhance lung cancer cell growth both in vivo and in vitro." (PMID 29340020, 2017). "EYA2 was reported upregulated and inversely correlated with PTEN expression in lung cancer tissue and NSCLC cell lines, leading to increased lung cancer cell proliferation." (PMID 31404976, 2019). "Collectively, the data demonstrated that there was an inverse correlation between EYA2 and PTEN in lung cancer samples." (PMID 29340020, 2017). "Uncontrolled and unlimited cell proliferation is a hallmark of cancer and another member of the Eyes Absent family, EYA2, has been shown to increase cell proliferation in lung cancer." (PMID 37292941, 2023). "High EYA2 level has been demonstrated to be a negative element for prognosis in lung cancer, while EYA2 predicted better clinical outcomes in colorectal cancer and pancreatic cancer." (PMID 30761270, 2019). "The expression of PTEN was negative correlated with EYA2 expression in lung cancer (Phi = −0.28, p = 0.017)." (PMID 29340020, 2017). "Then, the EYA2 expression in 86 lung cancer tissues and 20 non-tumor lung tissues was examined using immunohistochemisty." (PMID 29340020, 2017).
pancreatic cancer (8 papers, 2014 to 2023). "We found loss of tumoral Eya2 expression in 63% of pancreatic cancers (120/189 cases)." (PMID 24810906, 2014). "Although EYA2 cannot serve as an independent prognostic biomarker, high EYA2 expression was correlated with poor prognosis for pancreatic cancer patients." (PMID 30761270, 2019). "Reduction of EYA2 in pancreatic cancer cell lines increased cell proliferation, and stable EYA2 expression reduced metastasis in mouse xenographs." (PMID 30558204, 2018). "We also find evidence for epigenetic regulation of EYA2 in pancreatic cancers with both aberrant DNA methylation and chromatin marks in different pancreatic cancers." (PMID 24810906, 2014). "Here, we demonstrate that the majority of pancreatic cancers lose expression of the developmental transcription factor and phosphatase, EYA2." (PMID 24810906, 2014). "Epigenetic silencing of EYA2 is a common event in pancreatic cancers and stable expression EYA2 limits the growth and metastases of pancreatic adenocarcinoma." (PMID 24810906, 2014). "Knockdown of EYA2 in EYA2-expressing pancreatic cancer cells resulted in an increase in cell proliferation and stably-expressing EYA2 pancreatic cancer cells had reduced cell migration." (PMID 24810906, 2014). "The transcriptional changes after stable expression of EYA2 in pancreatic cancer cells included induction of genes in the TGFbeta pathway." (PMID 24810906, 2014). "Since aberrant methylation is a common mechanism of gene silencing in pancreatic cancer, and EYA2 has been shown to be hypermethylated in colon cancers, we investigated the role of epigenetic mechanisms in EYA2 silencing." (PMID 24810906, 2014). "We then used methylation-specific PCR (MSP) to assess EYA2 promoter methylation in 53 pancreatic cancers (9 cell lines, 23 primary pancreatic cancer tissues and 21 xenografts of primary pancreatic cancers) and 58 normal pancreatic tissues." (PMID 24810906, 2014). "Consistent with its role as a transcription factor, we identified many genes that were either upregulated or downregulated in the EYA2-expressing pancreatic cancer cells, many of which were involved in developmental processes, cell growth and adhesion." (PMID 24810906, 2014). "Bioinformatic analysis of our Serial Analysis of Gene Expression data revealed EYA2 mRNA as underexpressed in pancreatic cancers compared to pancreatic normal duct cells and HPDE, an immortalized non-neoplastic human pancreatic ductal epithelial line." (PMID 24810906, 2014). "To investigate the function of EYA2 in pancreatic cells, we established stable EYA2-overexpressing clones from Panc2.5 and Panc3.014 pancreatic cancer lines using the pcDNA6.2/cLumio-DEST containing the EYA2 transcript." (PMID 24810906, 2014). "Silencing of EYA2 expression in pancreatic cancer cell lines correlated with promoter methylation and histone deacetylation and was reversible with DNA methyltransferase and HDAC inhibitors." (PMID 24810906, 2014). "EYA2 knockdown in pancreatic cancer cell lines increased cell proliferation." (PMID 24810906, 2014). "Furthermore, EYA2 expression had a dramatic reduction in tumor growth in vivo both in subcutaneous and in orthotopic models, in two different pancreatic cancer cell lines and in multiple clones." (PMID 24810906, 2014). "We then examined EYA2 promoter methylation by bisulfite sequencing in normal HPDE cells and five pancreatic cancer cell lines." (PMID 24810906, 2014). "Several hundred genes have been identified as silenced in pancreatic cancers by global gene expression analysis in prior studies, but we focused on EYA2 because of its putative functions and because it has not been recognized previously as underexpressed in pancreatic cancer." (PMID 24810906, 2014).
ovarian carcinoma (6 papers, 2009 to 2025). A malignant neoplasm originating from the surface ovarian epithelium. "EYA2 (Eyes Absent Homolog 2) has been shown to be overexpressed in ovarian cancer cases and is associated with poorer survival outcomes, particularly in advanced-stage disease." (PMID 40422184, 2025). "For example, Eya2 is known to be upregulated in human ovarian cancer and associated with poor survival in advanced cases of ovarian cancer." (PMID 31317026, 2019). "A group of researchers has reported that elevated levels of EYA2 mRNA were observed in ovarian cancer and that the expression of EYA2 was correlated with tumor progression." (PMID 37156847, 2023). "EYA2 functions as a transcriptional coactivator inovarian cancer cell lines and ectopic expression of EYA2 promotesgrowth of ovarian cancer xenografts." (PMID 21423607, 2011).
colorectal cancer (4 papers, 2010 to 2023). A primary or metastatic malignant neoplasm that affects the colon or rectum. "Moreover, it was reported that the mRNA expression of EYA2 was generally reduced in colorectal cancer and higher EYA2 expression might predict a more favorable prognosis." (PMID 37156847, 2023).
lung adenocarcinoma (4 papers, 2016 to 2021). A carcinoma that arises from the lung and is characterized by the presence of malignant glandular epithelial cells. "Knockdown of EYA2 by siRNA reduced the proliferation through cell cycle G1 block and enhanced the apoptosis of lung adenocarcinoma cells." (PMID 30761270, 2019). "In lung adenocarcinoma, the expression of EYA2 was found upregulated in cancer tissues and may be involved in the progression of lung adenocarcinoma as a transcriptional activator." (PMID 34350290, 2021).
astrocytoma (3 papers, 2019 to 2023). "Research has shown that the upregulation of cyclin proteins and ERK signaling is promoted by the interaction between overexpressed EYA2 and Six1, which leads to increased proliferation and invasion of astrocytoma cells." (PMID 37156847, 2023). "In human astrocytoma, EYA2 promoted cell cycle progression of tumor cells via the up-regulation of cyclin D1 and cyclin E." (PMID 30761270, 2019).
liver cancer (3 papers, 2021 to 2024). An epithelial or non-epithelial malignant neoplasm that arises from the liver. "Eyes absent homolog 2 (EYA2) is considered a tumor suppressor gene in liver cancer, usually exhibiting a pattern of somatic mutations (p.Ala510Glu)." (PMID 38273295, 2024). "Moreover, we analyzed 61 somatic mutations of EYA2 in 26 of the 402 Chinese patients with liver cancer using the ICGC database, thus demonstrating a mutation frequency of 6.47%, which was higher than that in other countries." (PMID 34044846, 2021). "EYA2 was expressed at a low level in liver cancer cells compared to its expression in a wide range of cancer cells by CCLE database." (PMID 34044846, 2021). "The expression of EYA2 was down-regulated in HCC and associated with tumor size (P = 0.001), Barcelona Clinic Liver Cancer stage (P = 0.016) and tumor differentiation (P = 0.048)." (PMID 34044846, 2021). "Meanwhile, the delivery of EYA2 can be used to treat orthotopic liver cancer in nude mice, which showed that EYA2 may be a target for liver cancer treatment." (PMID 36750914, 2023).
pancreatic adenocarcinoma (3 papers, 2014 to 2021). "Complete loss of Eya2 protein expression was observed in the tumor cells of 63.5% of primary pancreatic adenocarcinomas (120 of 189 cases), while expression of Eya2 was found in normal ductal cells of 99.5% of cases." (PMID 24810906, 2014). "On the other hand, a stable knockdown of EYA2 increases cell proliferation and metastasis of pancreatic adenocarcinoma." (PMID 34044846, 2021). "On the contrary, one previous research demonstrated that EYA2 overexpression was an unfavorable molecule for tumor growth of pancreatic adenocarcinoma in orthotopic models." (PMID 30761270, 2019). "In pancreatic adenocarcinoma, stable overexpression of EYA2 up-regulated transforming growth factor-β (TGF-β) signaling which is an important inducer of EMT." (PMID 30761270, 2019). "Overall, methylation of the EYA2 promoter was found in 22.7% of pancreatic adenocarcinomas versus 6.9% of normal pancreatic tissues (p=0.019)." (PMID 24810906, 2014). "However, the Vincent’s group demonstrated that deletion of EYA2 promoted pancreatic adenocarcinomas progression through the disruption of TGF-β pathway." (PMID 34044846, 2021). "We then examined the expression of Eya2 protein in 189 primary pancreatic adenocarcinomas and adjacent normal and non-neoplastic pancreas by performing immunohistochemistry on tissue microarrays." (PMID 24810906, 2014).
type 2 diabetes (3 papers, 2021 to 2026). "The C alleles for both rs55966194 and rs59791349 are associated with higher EYA2 expression and increased risk of type 2 diabetes." (PMID 34699533, 2021). "EYA2 is involved in DNA repair and has, besides type 2 diabetes, also been reported to associate with triglyceride levels and waist-hip ratio." (PMID 33407418, 2021). "Both regulatory elements contained variants associated with adipose tissue expression of EYA2 and type 2 diabetes." (PMID 34699533, 2021). "Also, at this locus, a second candidate regulatory element is an adipose-specific peak not detected in SGBS and which contains variant rs59791349, which is a proxy variant for an adipose eQTL for EYA2 and a GWAS locus for type 2 diabetes." (PMID 34699533, 2021).
breast tumor (2 papers, 2017 to 2019). "EGFR promotes breast tumor growth and lung metastasis by HIF1α repression of miR-338-3p and subsequent activation of EYA2." (PMID 28703807, 2017). "To confirm the in vitro phenotype of the EGFR/miR-338-3p/EYA2 pathway, we first investigated the effect of the pathway on breast tumor growth by injecting 4T1 cells harboring the indicated constructs and/or the miR-338-3p inhibitor into the mammary fat pads of BALB/c mice." (PMID 28703807, 2017). "Here, we show that EGFR promotes breast tumor growth and metastasis by downregulating the tumor suppressor micoRNA-338-3p (miR-338-3p) and activating the EYA2 (EYA transcriptional coactivator and phosphatase 2) oncoprotein." (PMID 28703807, 2017).
kidney cancer (2 papers, 2010 to 2023). Primary or metastatic malignant neoplasm involving the kidney. "The level of mRNA of EYA1 was highly expressed in kidney cancer, while EYA2/3/4 was expressed low in cancer tissues with adjacent normal tissues (respectively)." (PMID 37156847, 2023).